ATM (ATM serine/threonine kinase)
Diseases named in the same sentence as ATM in open-access papers (continued):
Sharing a sentence is not in itself a finding about the gene and the disease.
breast cancer (continued). "Additionally, the difference in the recommendations from the UKCGG/UKGTN meeting and the TD have resulted in further variation in practice, particularly for the moderate risk breast cancer predisposition genes ATM and CHEK2." (PMID 33568439, 2021). "To investigate a possible role for ATM-dependent PTEN phosphorylation in breast cancer, we bred the Pten398A allele on the background of mice expressing the inactivated neu (Erbb2) fusion gene under the transcriptional control of the mouse mammary tumor virus (MMTV) promoter/enhancer (MMTVneu)." (PMID 34059798, 2021). "For example, ATM is an established breast cancer and pancreatic cancer predisposition gene and pathogenic variants in ATM have also been implicated in susceptibility to gastric cancer and prostate cancer, suggesting that the ATM tumor spectrum is likely broad." (PMID 34262154, 2021). "Therefore, the current study aims to clarify the pooled relationship between ATM variants and breast cancer." (PMID 33402103, 2021). "In the current study, the prevalence of ATM variants in breast cancer patients was evaluated." (PMID 34493284, 2021). "On the contrary, the impact of ATM mutations on other cancer susceptibility is still controversial, as for breast cancer, as evidenced by data regarding the spectrum and frequency distribution of ATM mutations in breast cancer." (PMID 32858941, 2020). "In conclusion, the hypothesis is that the risk may be higher for certain mutations, including missense mutations responsible for abnormal ATM protein, thus involvement of ATM gene mutations in breast cancer may be crucial in particular families." (PMID 32858941, 2020). "ATM is a known intermediate penetrance cancer predisposition gene, as heterozygous carriers of ATM germline pathogenic variants are at increased risk of developing several types of malignancies, including breast cancer (BC) and PC." (PMID 32325837, 2020). "Importantly, in the Netherlands, female ATM mutation carriers have an adjusted screening program for breast cancer." (PMID 31709473, 2020). "Moreover, it has been demonstrated that rare missense variants of moderate-risk genes, such as ATM, confer an increased risk for early-onset breast cancer." (PMID 32127026, 2020). "Thus, mutations in ATM result in a moderate risk of cancer and a recent multicentre case-control study includes for ATM some genetic variants associated with an increased risk of breast cancer." (PMID 32858941, 2020). "The ATM c.8934_8935delTG variant was found in the III.12 breast cancer patient." (PMID 32756499, 2020). "Compared with parental sham-treated cells, radioresistant breast cancer cells present elevated radioresistance, enhanced malignancy, increased expression of Ataxia-telangiectasia mutated (ATM), and increased DNA damage repair efficiency, as reflected by accelerated γ-H2AX kinetic." (PMID 32174787, 2020). "In 52 breast cancer samples, low ATM levels compared to normal breast tissue were associated with high tumor grade, while ATM loss was associated with distant metastasis (P < 0.001), worse disease free survival (DFS) (P < 0.001) and cancer-specific survival (CSS) (P < 0.001)." (PMID 33224881, 2020). "Also, parents confirm the importance that there is an advantage for heterozygous ATM carriers as the increased risk for breast cancer requires early screening." (PMID 31709473, 2020). "Bernstein suggested that common ATM variants may exert a protective effect and reduce contralateral breast cancer risk, while rare ATM missense, deleterious variants may act synergistically with radiation exposure to increase this risk." (PMID 31935898, 2020). "ATM had been known to be linked to breast cancer predisposition in BRCA-negative families." (PMID 32756499, 2020). "The ataxia telangiectasia mutated (ATM) gene was the most reported in LA breast cancer cases." (PMID 31658756, 2019).
breast cancer (continued). "In ATM, one missense mutation, p.Val2424Gly (c.7271T>G) confers a higher risk of breast cancer than truncating ATM variants (up to 52% in one study; 95% CI 28–80%) and may do so by acting as a dominant negative." (PMID 30832243, 2019). "Therefore, ATM deficiency in MYC overexpressed breast cancer will be expected to promote aggressive breast cancers." (PMID 30746633, 2019). "However, high risk has been reported for contralateral breast cancer in subjects with ATM missense mutations who underwent radiotherapy, indicating a lack of proper treatment with radiotherapy." (PMID 30975222, 2019). "Not only AT patients, but also certain ATM heterozygous mutation carriers show a significantly reduced life expectancy due to cancer and ischemic heart disease; in particular, female carriers having particular alleles have an increased risk of breast cancer." (PMID 31443742, 2019). "Germline mutations in ATM gene are thought to contribute to breast cancer susceptibility." (PMID 30886832, 2019). "We finally applied TSA to the meta-analytic results to establish whether the accumulated evidence on the association of ATM rs1801516 with late skin complications of radiotherapy for breast cancer might be sufficient to draw reliable conclusions." (PMID 31756226, 2019). "In haplotype analysis, haplotypes A‐C‐G‐G (in order of rs189037, rs3092856, rs1801516 and rs373759) and A‐C‐A‐A in ATM gene were significantly associated with 1.98‐fold and 6.04‐fold increased risk of breast cancer (95% CI: 1.36‐2.90 and 1.65‐22.08, respectively)." (PMID 29691986, 2018). "We tested the hypothesis that genetic variation in ATM and BMI‐1 genes can alter the risk of breast cancer through genotyping 6 variants among 524 breast cancer cases and 518 cancer‐free controls of Han nationality." (PMID 29691986, 2018). "To test this hypothesis, we genotyped 4 variants in ATM gene and 2 variants in BMI‐1 gene in 524 breast cancer cases and 518 cancer‐free controls from Heilongjiang province, China to see whether they can alter the risk of breast cancer." (PMID 29691986, 2018). "The findings of this study indicate that common genetic variations in the XRCC2, PHB, CDH1 and ATM genes, respectively may influence susceptibility to breast cancer among Sri Lankan postmenopausal women." (PMID 29433565, 2018). "For the moderate-risk homologous recombination repair (HRR) breast cancer genes ATM, BARD1, CHEK2, and NBN, 3.3% (p = 7.2 × 10− 04) of unselected pancreatic cancer cases carried a clearly pathogenic variant, and weighted inclusion of HiP-VUS increased the proportion to 5.1% (p = 2.3 × 10− 08)." (PMID 29945567, 2018). "Therefore, in this study, we investigated the frequency and spectrum variants of the kinase domain in the ATM gene in a series of women with breast cancer." (PMID 29678143, 2018). "Furthermore, we also used a PTV-ALFRED model to analyze each of the 17 cancer types and three genes were significant in at least one individual cancer type (FDR = 0.2, four associations: BRCA2 and ATM in breast cancer, BRCA1 and BRCA2 in ovarian cancer)." (PMID 29973584, 2018). "Considering the increased risk conferred by a single allele may be small, we further explored the joint impact of ATM genetic variants on breast cancer susceptibility." (PMID 29691986, 2018). "Besides the candidate ATM gene, we have assessed the association between BMI‐1 gene 2 variants and breast cancer risk." (PMID 29691986, 2018). "In particular, we have identified 2 variants in ATM gene, rs189037 and rs1801516, which may play a dominant role, as well as a possible joint role, in susceptibility to breast cancer risk." (PMID 29691986, 2018).
breast cancer (continued). "The mean age of our cases with breast cancer was 53.76 years, prompting us to speculate that the magnitude of ATM gene in predisposition to breast cancer was relatively strong in Chinese." (PMID 29691986, 2018). "Moreover, numerous epidemiological studies have indicated the contribution of ATM variants to breast cancer." (PMID 29678143, 2018). "Similarly, quantitative IHC of ATM in breast cancer identified a smaller subgroup of ATM-deficient patients than does standard histopathology, however in both of these studies ATM-loss was associated with poor DFS." (PMID 28418844, 2017). "Consistent with previous reports,5–7, 9, 11–13PALB2 c.3113G>A (p.Trp1038*), PALB2 c.1592delT (p.Leu531Cysfs) and ATM c.7271T>G (p.Val2424Gly) were found to be associated with substantially increased risk of breast cancer all with associated relative risk estimates of 3.44 or greater." (PMID 27595995, 2016). "The increased risk of breast cancer in ATM carriers was then confirmed by direct ATM sequencing in breast cancer cases compared to controls and ATM is now considered a moderate-penetrance cancer susceptibility gene in BRCA1/2-negative patients with familial early-onset breast cancer." (PMID 27599564, 2016). "Besides early onset-breast cancer, ATM carriers have been reported to be more susceptible to other types of cancer, such as digestive tract, lung, and thyroid cancers." (PMID 27599564, 2016). "While the spectrum of ATM mutations in classical A-T patients is well established, the pattern of ATM mutations and their role in breast cancer etiology remains unclear." (PMID 25625042, 2015). "Our results support the hypothesis that ATM heterozygotes carrying low penetrance ATM mutant alleles are at risk for breast cancer." (PMID 25625042, 2015). "Thus, the NGS technique is a promising approach to better estimate the number of ATM variants related to breast cancer." (PMID 25625042, 2015). "In addition, evidence of potential ATM mutations was observed in 7 of the 100 breast cancer cases analyzed." (PMID 25625042, 2015). "Our results corroborate the hypothesis that sporadic breast tumors may occur in carriers of low penetrance ATM mutant alleles and these mutations confer different levels of breast cancer risk." (PMID 25625042, 2015). "However, further functional studies to evaluate the biological effects of the potential ATM missense mutations observed in breast cancer patients and large case–control studies using NGS (amplicon and/or exome sequencing) are needed." (PMID 25625042, 2015). "To date, most of the ATM mutations observed in breast cancer patients, including the data reported here, are missense mutations distributed throughout the ATM gene, but mainly outside of the PI-3 K domain or other putative functional domains defined by sequence similarity." (PMID 25625042, 2015). "The data presented in this study provide a tantalizing possibility for a similar synthetic lethality targeting in BER-deficient ER+ breast cancers using inhibitors of DSB repair pathway such as those targeting ATM, ATR, and DNA-PKcs that are currently undergoing pharmaceutical drug development." (PMID 25111287, 2014). "Low expression of ATM observed in breast cancer tissue was frequently related to the accumulation of high rates of DNA mutations and to tumor progression; however, ATM expression is a complex process, and breast cancer onset can be influenced by several mechanisms." (PMID 25247188, 2014). "In our case-control mutation screening analysis of ATM, we also found that evidence for rMS that predispose to breast cancer was limited to rMS with Align-GVGD severity scores of greater than C0 that fall in the key functional domains of the protein that are central to its enzymatic activity." (PMID 24894818, 2014).
breast cancer (continued). "Single nucleotide polymorphisms of DNA repair genes have been associated with increased risk of breast cancer and recently, variants of the ATM gene, a key regulator of the cellular response to repair DNA damage, has also shown to be associated with altered susceptibility towards breast cancer." (PMID 24811059, 2014). "Additionally, aberrant overexpression of miR421 influences ATM posttranscriptional downregulation and this is associated with poor prognosis in sporadic breast cancer." (PMID 25247188, 2014). "This suggests that the increase in the mRNA level of ATM in the WBC of the carriers could be an indication for the potential predisposition of those individuals for developing breast cancer." (PMID 25403427, 2014). "Indeed, heterozygous ATM mutations are associated with up to a fivefold increased risk of breast cancer development, depending on the type of mutation." (PMID 24681585, 2014). "In the current study, patient SM-46, who was found to carry an exon 4 deletion in the ATM gene, also had a pathogenic mutation in the BRCA2 gene; therefore, the involvement of the ATM intragenic deletion with breast cancer predisposition in this particular case remains to be clarified." (PMID 24884479, 2014). "In addition to breast cancer, a next-generation sequencing study recently identified ATM heterozygous mutations in the germline of patients with familial pancreatic cancer and point to ATM as a novel pancreatic ductal adenocarcinoma predisposition gene." (PMID 24681585, 2014). "In addition to breast cancer, ATM mutations have been identified significantly in lung and colon cancer." (PMID 24681585, 2014). "Wang et al85 studied 360 samples from Han Chinese and reported that, by interacting with BRCA1 rs4793191 and BRCA2 rs9567623, the ATM polymorphism rs611646 might have a role in breast cancer risk." (PMID 23318652, 2013). "This is the case for mutations in the PALB2, BRIP1 and ATM genes, where heterozygotes have an increased lifetime risk of breast cancer, and homozygotes are diagnosed with multisystemic genetic syndromes (Fanconi’s anaemia for the first 2 genes and ataxia-telangiectasia for the latter)." (PMID 23570263, 2013). "A postulated mechanism is that underlying etiology predisposes both tumor types (mutation of ATM gene or infection by Epstein-Barr virus) or that the CLL may express a B-cell receptor with affinity for an undefined breast cancer antigen." (PMID 24151510, 2013). "We show that ATM-depletion confers sensitivity to olaparib in both cell lines and a mild sensitivity to iniparib in the MCF-7 cells indicating that ATM mutation/inactivation might be consider in the selection of breast cancers responsive to PARP inhibition." (PMID 24252502, 2013). "Truncating mutations in ATM appear to confer an about three-fold increased breast cancer risk to heterozygous carriers, and heterozygotes may account for 0 · 5-1% of most populations." (PMID 24025454, 2013). "Biallelic mutations of the ATM gene cause ataxia telangiectasia, which manifests as cerebellar ataxia, immune deficiency, and a variety of tumors such as leukemia, lymphoma, glioma, medulloblastoma, and breast cancer." (PMID 23318652, 2013). "Based on these observations, we asked whether ATM deficiency plays a similar role in breast cancer, the solid tumor linked to ATM germline mutations." (PMID 24252502, 2013). "It remains to be confirmed in a germline mutations study whether ATM is the breast cancer susceptibility gene in Chinese." (PMID 23318652, 2013). "In addition, IVS 22–77 T>C is in tight linkage disequilibrium with IVS48 _ 238 G, another ATM variant allele that was shown to be an association with breast-cancer risk." (PMID 22276117, 2012).
breast cancer (continued). "The risk estimates from this study suggest that women carrying the pathogenic variant, ATM c.7271T > G, or truncating mutations demonstrate a significantly increased risk of breast cancer with a penetrance that appears similar to that conferred by germline mutations in BRCA2." (PMID 21787400, 2011). "ATM participates in multiple stress-related activities and plays a critical role in the maintenance of genome stability and integrity with mutations of ATM closely related to cancer predisposition including breast cancer." (PMID 21935375, 2011). "Separate analyses of the 15 families carrying the ATM c.7271T > G variant found that this variant increased breast cancer risk by a factor of 8.0 (95% CI, 2.3 to 27.4; P = 0.0005) compared with 4.4 (95% CI, 0.70 to 28.1; P = 0.053) for families with other variants." (PMID 21787400, 2011). "In this respect, individuals with anomalies of the ATM (ataxia telangiectasia) protein/gene are of particular interest as they may be at risk of both breast cancer and clinical radiosensitivity." (PMID 20678261, 2010). "After subgroup analyses according to ethnicity, we found that the ATM D1853N polymorphism was associated with a significantly increased risk of breast cancer in South American population (heterozygote comparison and dominant model) but not in European and mixed populations." (PMID 20799949, 2010). "Firstly, the ATM D1853N polymorphism may present with different frequencies in different populations and as a result may be associated with different degrees of breast cancer risk among different ethnic populations." (PMID 20799949, 2010). "The pathological risk for clinical radiosensitivity and/or breast cancer associated with ATM mutations is considered to be low but in most risk assessments this risk could better be described as uncertain due to the omission of functional data." (PMID 20678261, 2010). "A larger study including A-T families could help refine ATM protein thresholds for risk of both clinical radiosensitivity and breast cancer." (PMID 20678261, 2010). "Heterozygous carriers of ATM-mutations have an increased risk for the development of breast cancer." (PMID 20799949, 2010). "However a large number of the detected ATM mutations in familial breast cancer cases are actually result in truncated gene products resulting in no expression of ATM protein from the mutant allele." (PMID 20175908, 2010). "ATM exon 24 allele counts from 66 independent breast cancer cases and 126 unrelated controls." (PMID 21187953, 2010). "An excess of group-specific variants at the ATM gene has been reported in breast cancer." (PMID 21187953, 2010). "Although the effect of pathogenic DDRP gene mutations on breast cancer risk seems evident, the role of most ATM missense mutations remains unclear." (PMID 17428320, 2007). "The aim of this study was to investigate the difference in type and frequencies of ATM variants and haplotypes in association with risk of breast cancer, as well as subcutaneous and cutaneous radiation induced adverse side effects, development of costal fractures and pleural thickening." (PMID 17623063, 2007). "The literature shows that ATM missense mutation carriers have an increased risk for breast cancer." (PMID 17428320, 2007). "The first suggestion that ATM might be a breast cancer susceptibility gene came from studies reporting an increased breast cancer risk among obligate heterozygous mutation carriers in A-T families." (PMID 16914028, 2006). "We also aimed to investigate whether there are other ATM mutations or variants contributing to breast cancer risk in our population." (PMID 16914028, 2006). "A strong candidate for a breast cancer predisposition gene is ATM (MIM# 607585)." (PMID 16622469, 2006).